PDCD1 (programmed cell death 1)
Diseases named in the same sentence as PDCD1 in open-access papers (continued):
Sharing a sentence is not in itself a finding about the gene and the disease.
malaria (5 papers, 2016 to 2023). Malaria is a serious and sometimes fatal disease caused by a parasite that commonly infects a certain type of mosquito which feeds on humans. "Evidence of malaria induced immunosuppression within our data was also observed in NK and γδ T cell subsets, where multiple co-inhibitory receptors were upregulated during infection (including TNFRSF4, TNFRSF9, TNFRSH18, HAVCR2, LAG3, and PDCD1)." (PMID 37968278, 2023). "In malaria, work in both human and murine models has reported the upregulation of immune inhibitory markers such as T-cell immunoglobin and mucin domain-3 (TIM-3), lymphocyte-activation gene-3 (LAG-3) and programmed cell death-1 (PD-1) during acute infections." (PMID 31316497, 2019). "Previous studies using the P. chabaudi (Pch) mouse model to understand the reason for chronic malaria, found that mice with a deletion of programmed cell death-1 (PD-1KO) generate sterile immunity unlike wild type (WT) mice." (PMID 27217330, 2016).
mucosal melanoma (5 papers, 2019 to 2026). A melanoma that arises from a mucosal site. "Metastatic mucosal melanoma responds poorly to anti–programmed cell death-1 (PD-1) monotherapy." (PMID 31403867, 2019).
oral cancer (5 papers, 2020 to 2026). "Background and objectives Prior studies have shown that patients with oral cancer overexpress programmed cell death 1 (PD-1) and programmed cell death ligand 1 (PD-L1) in cancer cells and immunocompetent lymphocytes." (PMID 39991356, 2025). "BME treatment suppressed the expression of the immune checkpoint gene PDCD1/PD1 and the proinflammatory genes IL1b, IL23a, and s100a9, which were reported to have elevated expression during oral cancer development." (PMID 34572990, 2021).
pneumonia (5 papers, 2020 to 2025). An acute, acute and chronic, or chronic inflammation focally or diffusely affecting the lung parenchyma, caused by an infection in one or both of the lungs (by bacteria, viruses, fungi, or mycoplasma.). "Soluble programmed cell death 1 (sPD-1) and its ligand (sPD-L1) have emerged as potential biomarkers for early identification and risk stratification in patients with severe pneumonia (SP)." (PMID 40636377, 2025).
rectal cancer (5 papers, 2019 to 2025). A primary or metastatic malignant neoplasm that affects the rectum. "Our TWAS and MR analyses suggested that increased (rather than decreased, replicating the use of an inhibitor) expression of PDCD1 reduced risk of rectal cancer." (PMID 40447568, 2025). "Another study suggested that locally advanced rectal cancer with mismatch-repair deficiency is exceptionally sensitive to single-agent programmed cell death-1 blockade, which is a key mediator of immune suppression (within the tumor microenvironment) in NACRT." (PMID 39449806, 2024). "Additionally, we found associations with unique anatomical subsite cancers: LTBR with risk of proximal colon cancer and PDCD1 with risk of rectal cancer." (PMID 40447568, 2025).
sarcoidosis (5 papers, 2017 to 2025). Sarcoidosis is a multisystemic disorder of unknown cause characterized by the formation of immune granulomas in involved organs. "Microarray analysis of sarcoidosis PBMC revealed a positive correlation between the expression of PDCD1, the gene encoding PD-1, and basic leucine zipper transcription factor ATF-like (BATF) (r = 0.58, p = 0.005)." (PMID 29234685, 2017). "Surprisingly, lymphoid cells in non–sarcoidosis-affected skin specifically induced immune checkpoint genes, including TIGIT, LAG3, and PDCD1." (PMID 39225100, 2024).
thymoma (5 papers, 2023). A neoplasm arising from the epithelial cells of the thymus. "In addition, immune checkpoint inhibitors, such as programmed cell death 1 or cytotoxic T-lymphocyte-associated protein 4 could induce these diseases by regulating T cell activation instead of thymoma." (PMID 37781409, 2023). "A 45-year-old thymoma patient was admitted to our hospital after receiving anti-programmed cell death-1 treatment with sintilimab 14 days later, accompanied by abdominal pain, intermittent chest tightness and dizziness." (PMID 37058040, 2023). "PDCD1 expression was similarly greatly raised in thymoma, whereas CSF3 expression was significantly reduced." (PMID 37644514, 2023). "We found that PDCD1 expression was enhanced in the thymoma, but CSF3 expression decreased." (PMID 37644514, 2023). "The immune infiltration analysis of aberrant PDCD1 and CSF3 expression revealed that T cells, including Th2 cells, CD8 + T cells, and Th17 cells, were highly enriched and activated within the thymoma." (PMID 37644514, 2023). "Using the TCGA dataset, we focused on the expression pattern of PDCD1 and CSF3 in thymoma tissue." (PMID 37644514, 2023). "We evaluated the effect of PDCD1 and CSF3 on thymoma immune infiltration patterns." (PMID 37644514, 2023).
tuberculosis (5 papers, 2016 to 2025). A chronic, recurrent infection caused by the bacterium Mycobacterium tuberculosis. "A patient with homozygous LOF in PDCD1 was recently reported with autoimmune manifestations and tuberculosis (TB)." (PMID 36189259, 2022).
ankylosing spondylitis (4 papers, 2006 to 2024). An autoimmune chronic inflammatory disorder characterized by inflammation in the vertebral joints of the spine and sacroiliac joints. "A recent study highlights the association between programmed cell death 1 (PDCD1) gene polymorphism and ankylosing spondylitis in the Korean population." (PMID 38965390, 2024).
chronic lymphocytic leukemia (4 papers, 2023 to 2025). "Prior research has highlighted the significant involvement of miR-15/16 in chronic lymphocytic leukemia by targeting PDCD1 expression." (PMID 39640266, 2024). "Among these, PDCD1 was chosen for further investigation due to its significant role in immune checkpoint regulation and its growing importance in drug resistance pathways, especially in the context of ibrutinib-treated chronic lymphocytic leukemia (CLL)." (PMID 41249728, 2025). "The recognition of PDCD1 as a shared hub gene in two separate datasets (GSE249956 and GSE98206), along with its potential for drug targeting, indicates that immune checkpoint–mediated immune evasion might play a role in ibrutinib resistance in chronic lymphocytic leukemia (CLL)." (PMID 41249728, 2025).
colon adenocarcinoma (4 papers, 2021 to 2025). "Growth of MC-38 colon adenocarcinoma cells injected in Pdcd1-mCherry-SMASh homozygous knock-in (KI) mice was repressed by ASV or GRV." (PMID 35734392, 2022).
colorectal tumor (4 papers, 2021 to 2025). "We downloaded single cell RNA-seq datasets (GSE178341) and analyzed PDCD1 and IFN-I expression profiles in human colorectal tumors." (PMID 38995014, 2024).
cutaneous T cell lymphoma (4 papers, 2020 to 2023). "In addition, we studied a second cohort of patients with cutaneous T cell lymphoma (CTCL) that were either PDCD1 wild type or PDCD1 mutant at initial diagnosis." (PMID 37723306, 2023).
dermatitis (4 papers, 2018 to 2025). An inflammatory process affecting the skin. "Use of immune checkpoint inhibitors that target programmed cell death-1 (PD-1) can lead to various autoimmune-related adverse events (irAEs) including psoriasis-like dermatitis." (PMID 33060784, 2020). "Seven patients had serious skin disorders or hypersensitivity, six of whom had prior anti-programmed cell death-1 (PD-1) antibodies 5–35 days before starting vemurafenib." (PMID 28674996, 2018). "Further mechanistic studies revealed that FMT treatment induced CD103 DCs and programmed cell death ligand 1 (PD-L1)/programmed cell death 1 (PD-1) expression in skin-draining lymph nodes and promoted Treg production to induce immune tolerance and suppress skin inflammation." (PMID 40771816, 2025).
influenza infection (4 papers, 2021 to 2025). "Firstly, the identified biomarkers (e.g., Ccl8, Pdcd1, kynurenine, L-glutamine) and the influenza risk scoring system remain unvalidated experimentally." (PMID 40475788, 2025). "We identified a range of potential biomarkers, including genes such as Ccl8, Pdcd1, Gzmk, and metabolites like kynurenine, adipoyl-carnitine, L-glutamine, which can be used for monitoring influenza risk." (PMID 40475788, 2025).
squamous non-small cell lung cancer (4 papers, 2016 to 2022). "Nivolumab targets the immune-check point inhibitor programmed cell death-1 and was used for squamous non-small cell lung cancer." (PMID 29441072, 2018).
testicular germ cell tumor (4 papers, 2022 to 2025). A germ cell tumor arising from the testis. "Additionally, UPF3B expression was positively correlated with most immunoinhibitors, including TGFBR1, IL10RB, CD160, CD274, TIGIT and PDCD1 in UVM, OV, KIHC, and LIHC, but negatively associated with the expression of majority genes in STAD and Testicular Germ Cell Tumors (TGCT)." (PMID 36194583, 2022). "The results showed that in BLCA (P < 0.001), BRCA (P < 0.001), COAD (P < 0.05), and THCA (P < 0.001), PCSK9 was positively correlated with PDCD1, CD274, and CTLA4 but negatively correlated in HNSC (P < 0.05) and testicular germ cell tumor (TGCT) (P < 0.01)." (PMID 38600469, 2024).
Thyroid (4 papers, 2020 to 2024). "Thyroid-related adverse events are frequently associated with anti-programmed cell death 1 (PD-1) or anti-programmed cell death-ligand 1 (PD-L1) agents." (PMID 34771631, 2021).
esophageal adenocarcinoma (3 papers, 2017 to 2025). A malignant tumor with glandular differentiation arising predominantly from Barrett mucosa in the lower third of the esophagus. "A recent study showed that nivolumab, the first programmed cell death-1 (PD-1) inhibitor, plus chemotherapy had superior OS and PFS with tolerable toxicity profile in patients with previously untreated advanced gastric, gastroesophageal junction, or esophageal adenocarcinoma." (PMID 34926309, 2021).
Gynecological Cancers (3 papers, 2021 to 2023). "In gynecologic cancers, EC showed the highest overexpression of programmed cell death 1 (PD-1, CD279) and programmed cell death ligand 1 (PD-L1, CD274): 40–80% in endometrioid carcinoma, Serous carcinomas accounted for 10–68% of tumors, and clear cell tumors accounted for 23–69%, respectively." (PMID 37853361, 2023). "Among gynecological cancers, EC displays the highest overexpression of programmed cell death 1 (PD-1, CD279) and programmed cell death ligand-1 (PD-L1, CD274): 40–80% for endometrioid cancers, 10–68% for serous tumors, 23–69% for clear cells tumors, respectively." (PMID 34199461, 2021).
Hyperglycemia (3 papers, 2022 to 2025). An increased concentration of glucose in the blood. "Beyond acute metabolic stress, the emerging concept of metabolic memory suggests that prior hyperglycemia may imprint checkpoint gene loci, such as PDCD1 and CD274, with persistent epigenetic marks, although direct demonstration in vascular tissues is required for validation." (PMID 41463504, 2025).
hypothyroidism (3 papers, 2020 to 2024). Abnormally low levels of thyroid hormone.
immune deficiency (3 papers, 2019 to 2022). "Over the last decade, monoclonal antibodies targeting programmed cell death protein 1 (PD-1, also known as PDCD1 and CD279) or programmed cell death ligand 1 (PD-L1, also known as CD274 and B7-H1) to restore tumor-induced immune deficiency have emerged as a promising treatment." (PMID 35139879, 2022).
inflammatory bowel disease (3 papers, 2021 to 2025). A spectrum of small and large bowel inflammatory diseases of unknown etiology. "Its abundance is inversely correlated with inflammatory bowel disease and type 2 diabetes, but positively correlated with responses to programmed cell-death 1 (PD-1) or programmed cell-death-ligand 1 (PD-L1) checkpoint inhibitors in cancer immunotherapy." (PMID 35896748, 2022).
lymphoproliferative disorders (3 papers, 2021). "This is the first study evaluating a possible association between PDCD1 polymorphisms and the risk of HCV‐related lymphoproliferative disorders." (PMID 32937024, 2021).
Lynch syndrome (3 papers, 2015 to 2024). An autosomal dominant hereditary neoplastic syndrome characterized by the development of colorectal carcinoma and a high risk of developing endometrial carcinoma, gastric carcinoma, ovarian carcinoma, renal pelvis carcinoma, and small intestinal carcinoma. "Interestingly, in vitro GM102 positively cooperates with pembrolizumab, an anti-PDCD1 (programmed cell death 1) antibody, which is useful in cancers with microsatellite instability (Lynch syndrome) with profiling lymphocytes towards TH1 cells." (PMID 39351532, 2024).
meningioma (3 papers, 2021 to 2025). A generally slow growing tumor attached to the dura mater. "In accordance with higher infiltrations of immune and stromal cells and higher expression of classic immune checkpoints: CD86, PDCD1, and LAIR1, cluster 1 meningiomas might be more sensitive to immunotherapy." (PMID 41050085, 2025).
neuroblastoma (3 papers, 2018 to 2024). Neuroblastoma (NB) is the most common solid, extracranial childhood tumor. "Early studies of checkpoint inhibition in neuroblastoma have not been successful; thus, the benefit of blocking the programmed cell death 1 (PD1)/PD-L1 axis for enhanced immunotherapy needs to be better understood." (PMID 29377881, 2018). "Notably, we show that, despite the higher immunogenicity of induced dMMR (idMMR) neuroblastoma tumors, anti-programmed cell death 1 (PD1) therapy does not elicit a therapeutic effect against such tumors similar to adult malignancies treated with this treatment strategy." (PMID 36068918, 2023).
thyroid cancer (3 papers, 2021 to 2024). "We first assessed the prognostic relationship between PDCD1 and CD274 in patients with thyroid cancer." (PMID 34376710, 2021). "Then we explored the correlation between PDCD1 and CD274 and immune cells in thyroid cancer." (PMID 34376710, 2021).
toxic epidermal necrolysis (3 papers, 2023 to 2025). Toxic epidermal necrolysis (TEN) is an acute and severe skin disease with clinical and histological features characterized by the destruction and detachment of the skin epithelium and mucous membranes. "Tislelizumab, a programmed cell death-1 inhibitor approved for multiple malignancies, may induce Stevens-Johnson syndrome/toxic epidermal necrolysis (SJS/TEN)—a rare but potentially fatal severe drug eruption—and early effective intervention is pivotal for reducing SJS/TEN-related mortality." (PMID 41346629, 2025).
uveal melanoma (3 papers, 2022 to 2025). A melanoma derived from melanocytes of the uveal tract. "Similarly, in uveal melanoma (UVM) and liver hepatocellular carcinoma (LIHC), CRABP2 expression is significantly correlated with seven of these immune checkpoint genes (LAG3, CTLA4, PDCD1LG2, HAVCR2, PDCD1, CD274, and TIGIT)." (PMID 39991584, 2025).
acquired immunodeficiency syndrome (2 papers, 2021 to 2023). "This study was to evaluate the safety and efficacy of programmed cell death 1 (PD - 1) inhibitors in patients with advanced cancer and HIV/acquired immunodeficiency syndrome (AIDS)." (PMID 37799470, 2023).
Adrenal insufficiency (2 papers, 2020 to 2023). Insufficient production of steroid hormones (primarily cortisol) by the adrenal glands. "This study aimed to establish a risk scoring system for adrenal insufficiency in patients receiving anti-programmed cell death 1 (PD-1) or anti-programmed cell death-ligand 1 (PD-L1) agents." (PMID 37631013, 2023).
alveolar soft part sarcoma (2 papers, 2021 to 2025). An alveolar soft part sarcoma occurring in adults. "Although the treatment of metastatic alveolar soft part sarcoma with antiangiogenic agents such as apatinib, bevacizumab, and sunitinib has not effectively prevented recurrence, antibodies targeting programmed cell death 1 and its ligand may improve survival rates in these patients." (PMID 34618750, 2021).
autoimmune hemolytic anemia (2 papers, 2025). Autoimmune hemolytic anemia (AIHA) is an autoimmune disorder in which various types of auto-antibodies are directed against red blood cells causing their survival to be shortened and resulting in hemolytic anemia. "Herein, we describe a case of immunotherapy-related autoimmune hemolytic anemia (irAIHA) in a patient with locally advanced mismatch repair-deficiency colorectal cancer treated with toripalimab, a programmed cell death 1 (PD-1) (ICI)." (PMID 41158457, 2025).
breast-invasive carcinoma (2 papers, 2025). "An increase in PDCD1 and CD274 expression was correlated with better overall survival (OS) and disease-specific survival (DSS) in TNBC and breast-invasive carcinoma." (PMID 40278313, 2025).
Cachexia (2 papers, 2022 to 2023). Severe weight loss, wasting of muscle, loss of appetite, and general debility related to a chronic disease. "Cancer cachexia is associated with poor prognosis in immunotherapy through the desensitization of programmed cell death-1 (PD-1)/PD-L1 inhibition." (PMID 37686634, 2023).
co-infection (2 papers, 2023 to 2025). "Furthermore, our results suggest that co-infection led to an upregulation of programmed cell death-1 (PD-1) in circulating T cells." (PMID 38156320, 2023).
liposarcoma (2 papers, 2022 to 2026). A usually painless malignant tumor that arises from adipose tissue. "Among dedifferentiated liposarcoma, undifferentiated pleomorphic sarcoma and leiomyosarcoma, it has been confirmed that tumors with high immunogenic gene profiles are accompanied by high levels of PDCD1 expression." (PMID 34982796, 2022).
lupus nephritis (2 papers, 2006 to 2008). Glomerulonephritis in the context of systemic lupus erythematosus. "For example, PDCD1 has been shown to be associated with lupus nephritis and anti-phospholipid antibodies in ethnic subgroups, and PTPN22 is primarily associated with anti-cyclic citrullinated peptide (anti-CCP) and rheumatoid factor (RF) autoantibody positive RA." (PMID 18516230, 2008).
lymph node metastases (2 papers, 2022 to 2025). "In patients receiving neoadjuvant anti-programmed cell death-1 (PD-1) immunotherapy by pembrolizumab, the sensitivity and specificity of PET/CT to predict lymph node metastasis was investigated before and after treatment." (PMID 35936721, 2022).
malignant mesothelioma (2 papers, 2021). A malignant neoplasm of the pleura or peritoneum, arising from mesothelial cells. "Immunotherapy based on two checkpoint inhibitors (ICI), programmed cell death 1 (PD-1, Nivolumab) and cytotoxic T-lymphocyte 4 (CTLA-4, Ipilimumab), has provided a significant improvement in overall survival for malignant mesothelioma (MM)." (PMID 34199066, 2021).
ovarian tumor (2 papers, 2018 to 2023). "The increased expression of SIGLEC1 is closely related to tumor formation and metastasis, and the increased expression of ICOS leads to poor prognosis and significantly increased PDCD1 expression in ovarian tumors." (PMID 37895197, 2023).
pancreatic adenocarcinoma (2 papers, 2021 to 2025). "But, we also found that mRNA expression of PD-1 (PDCD1) was higher in normal control than that in thyroid carcinoma (P<0.05) but no different was found between pancreatic adenocarcinoma and its normal control (P>0.05)." (PMID 34326692, 2021).
parasitic infections (2 papers, 2015 to 2021). "Several consecutive studies have confirmed that the PDCD1/PD-L pathway is exploited by a panel of viral and parasitic infections as target for immune evasion, mostly by increasing CD274 on APCs." (PMID 25940792, 2015). "Finally, other studies reported the upregulated expression of programmed cell-death 1 (PD-1) in virus-specific T cells, during malaria infections and other parasitic infections as an indicator of T cell exhaustion or persistent antigen stimulation." (PMID 34771539, 2021).